TBXA2R (thromboxane A2 receptor)
Diseases named in the same sentence as TBXA2R in open-access papers (continued):
Sharing a sentence is not in itself a finding about the gene and the disease.
lung fibrosis (2 papers, 2023 to 2024). "A recent study has identified an increased expression of the thromboxane A2 receptor (TBXA2R) in fibroblasts during lung fibrosis in HPS-PF mice and humans." (PMID 39457053, 2024). "TBXA2R links oxidative stress to fibroblast activation during lung fibrosis, and TBXA2R antagonists have been proposed for treating pulmonary fibrosis." (PMID 36614301, 2023).
Obesity (2 papers, 2019 to 2024). Accumulation of substantial excess body fat. "Consistent with the functional enrichment analyses, we identified hub genes related to blood vessel morphogenesis in the darkred module: TBXA2R, FZD4, COL15A1, and TBX2 were positively associated with maternal BMI and/or obesity and with birth weight." (PMID 31110514, 2019).
Sepsis (2 papers, 2021 to 2024). Sepsis is defined as life-threatening organ dysfunction caused by a dysregulated host response to infection. "Sepsis also induced increased gene expressions of ETA, while PPET1, ETB, and TBXA2R gene expressions were similar." (PMID 34925058, 2021).
bleeding disorders (1 paper, 2016). "Since the major role of TBXA2R involves platelet activation, this raises the possibility that direct therapeutic targeting of the receptor as an anti-cancer strategy may compromise haemostasis and would potentially be a contraindication for patients with bleeding disorders." (PMID 27487152, 2016).
bronchitis (1 paper, 2017). An acute or chronic inflammatory process affecting the bronchi. "Significant differences in the prevalence and risk of bronchitis were found in genotypes of LT-α and TNF-α, but not in ALOX5, LTC4S, TBXA2R, ADAM33, NOS1 and ORMDL3 in the Inuit populations residing both in Greenland and in Denmark." (PMID 28740106, 2017).
cerebral microbleeds (1 paper, 2017). Cerebral microbleeds are a group of pathological processes affecting the small arteries, arterioles, capillaries and venules of the brain, as detected by brain imaging techniques. "Interestingly, 30% of Fabry patients show cerebral microbleeds, which together with the downregulated Thrombospondin 1 (Thsd7a) and Thromboxane a2 receptor (Tbxa2r) can be related to a general deficit in blood coagulation pathways." (PMID 29422837, 2017).
cerebrovascular diseases (1 paper, 2022). "The use of thromboxane A2 receptor antagonists has a positive effect in the treatment of various types of cerebrovascular diseases." (PMID 35566778, 2022).
Hypertension (1 paper, 2025). The presence of chronic increased pressure in the systemic arterial system. "Six genes (PTGS2, TBXA2R, ZNF101, KCNJ2, MSRA, and CMTM5) have been reported to be associated with hypertension." (PMID 39854379, 2025).
oropharyngeal cancers (1 paper, 2020). Carcinoma, predominantly squamous cell, arising from the epithelial cells of the oropharynx. "Methylation statuses of the PTGIR and TBXA2R promoters were positively correlated with recurrence in patients with oropharyngeal cancer (OR, 2.99; 95% CI 1.13–7.92; P = 0.028 and OR, 5.21; 95% CI 1.63–16.67; P = 0.006, respectively)." (PMID 31969157, 2020). "Methylation of the PTGIR and TBXA2R promoters was positively correlated with recurrence in oropharyngeal cancer (P = 0.028 and P = 0.006, respectively)." (PMID 31969157, 2020). "Additional analysis including only patients with oropharyngeal cancer (n = 79) revealed a shorter DFS for methylated than for unmethylated PTGIR and TBXA2R (log-rank test, P = 0.003 and P = 0.009, respectively)." (PMID 31969157, 2020).
pneumonia (1 paper, 2017). An acute, acute and chronic, or chronic inflammation focally or diffusely affecting the lung parenchyma, caused by an infection in one or both of the lungs (by bacteria, viruses, fungi, or mycoplasma.). "Among the off-targets identified, further analysis was carried out for the two potentially novel proteins involved in AP-associated pneumonia, TBXA2R and PTAFR." (PMID 29077727, 2017). "Pneumonia in relation to the antipsychotics screened was indeed found to be associated with TBXA2R and PTAFR." (PMID 29077727, 2017). "TBXA2R appears to have been less extensively studied than PTAFR in the context of pneumonia, but has nevertheless been implicated in bronchial hyper-responsiveness as well as bronchial constriction in animal models, both of which may be risk factors for pneumonia." (PMID 29077727, 2017). "Two targets, thromboxane A2 receptor (TBXA2R) and plateletactivating factor receptor (PTAFR) were found to be novel AP target receptorspotentially associated with pneumonia." (PMID 29077727, 2017). "Findings on the potential role of TBXA2R and PTAFR in the increased risk of antipsychotic-associated pneumonia derived from CT-link were further investigated using Cytoscape." (PMID 29077727, 2017). "Biological pathways constructed using Cytoscape identified plausible biological links potentially leading to pneumonia downstream of TBXA2R and PTAFR." (PMID 29077727, 2017). "We hypothesize that the increased risk of pneumonia-like symptoms mediated by PTAFR and TBXA2R may be exerted through the control of capillary permeability at the alveolar level." (PMID 29077727, 2017). "The identified AP off-targets, TBXA2R and PTAFR, in black, are linked, either directly or indirectly, to a group of nodes, shown in blue, which likely contribute to the increased risk of developing pneumonia-related symptoms after activation of TBXA2Ror PTAFR." (PMID 29077727, 2017). "Findings from this study confirmed existing receptor targets for AP drugs but also provided two novel off-targets that may lead to AP-associated pneumonia, namely PTAFR and TBXA2R." (PMID 29077727, 2017). "The novel mechanisms concerning TBXA2R and PTAFR as potential mediators of pneumonia symptoms constitute an important finding of this study." (PMID 29077727, 2017).
prostate adenocarcinoma (1 paper, 2016). "Hence, a RT-PCR based approach was also used to clarify which promoters within the TBXA2R, namely Prm1 or Prm3, are regulating TPα and TPβ expression in human prostate tissue or in the prostate adenocarcinoma LNCaP and PC-3 cell lines." (PMID 27689401, 2016).
prostate neoplasm (1 paper, 2016). A neoplasm (disease) that involves the prostate gland. "Significant changes in the methylation landscape within the Prm1 and Prm3 regions of the TBXA2R were observed across a range of benign, precursor prostate neoplasms and increasing PCa staging." (PMID 27689401, 2016).
renal carcinoma (1 paper, 2023). A carcinoma arising from the epithelium of the renal parenchyma or the renal pelvis. "TBXA2R is up-regulated in various tumors, and data from the Cancer Cell Line Encyclopedia show significant up-regulation in renal cancer, although without specification of the type of renal cancer." (PMID 36834678, 2023).
small artery occlusion (1 paper, 2020). "The thromboxane A2 receptor (TBXA2R) gene regulated platelet aggregation, and the C allele of rs768963 polymorphism of TBXA2R was associated with both large artery atherosclerosis and small artery occlusion." (PMID 33352859, 2020).
thrombophilia (1 paper, 2023). A condition characterized by an abnormally high level of thrombi. "Moreover, we analyze two other clusters: one containing ADRA2A and TBXA2R, the only two thrombophilia-related genes mutated in the healthy subject and the other containing F2, the main antithrombin resistance-causing gene, which is mutated in all subjects." (PMID 37098010, 2023). "ADRA2A and TBXA2R are thrombophilia-related genes mutated in the healthy subject." (PMID 37098010, 2023). "Moreover, the ADRA2A and TBXA2R subnetwork is significantly enriched in“angiogenesis” (GO:0001525), “nervous system development” (GO:0007399) and “vasculogenesis” (GO:0001570) GO Biological Processes, all related to thrombophilia, or vascular disease." (PMID 37098010, 2023).
type 1 von Willebrand disease (1 paper, 2015). "Platelet G protein-coupled receptor genes P2RY1, F2R, F2RL3, TBXA2R and PTGIR were sequenced in 146 index cases with type 1 von Willebrand disease and the potential effects of identified single nucleotide variations were assessed using in silico methods and heterologous expression analysis." (PMID 26630678, 2015).
type 1 VWD (1 paper, 2015). "We have identified seven heterozygous SNVs affecting F2R, F2RL3, TBXA2R and PTGIR in 8 of 146 patients with a historical diagnosis of type 1 VWD who were enrolled in the MCMDM-1VWD study." (PMID 26630678, 2015).
urticaria (1 paper, 2018). A vascular reaction of the skin characterized by erythema and wheal formation due to localized increase of vascular permeability. "Polymorphisms in the TBXA2R gene have been associated with urticaria." (PMID 29588858, 2018).
vitamin D deficiency (1 paper, 2021). A nutritional condition produced by a deficiency of VITAMIN D in the diet, insufficient production of vitamin D in the skin, inadequate absorption of vitamin D from the diet, or abnormal conversion of vitamin D to its bioactive metabolites. "Vitamin D deficiency induced an increase in the immune positivity of thromboxane A2 receptor only in male animals." (PMID 34360792, 2021).
cancer (14 papers, 2005 to 2025). A tumor composed of atypical neoplastic, often pleomorphic cells that invade other tissues. "Mutation rates of TP and TXA2S in the TCGA pan-cancer dataset suggests that both targets are poorly mutated in cancer (1.1% for TBXA2R and 1.7% for TXAS1)." (PMID 36234768, 2022). "TBXA2R can activate a diverse range of signalling pathways and has been implicated in the pathogenesis of many diseases, including cancer." (PMID 27487152, 2016). "Transcription control is the primary mechanism of regulation over TBXA2R expression in most cancers." (PMID 36234768, 2022). "In a model of lung colony formation, it has been observed that thromboxane A2 receptor signaling enhanced tumor colonization via P-selectin-mediated platelets-cancer cells crosstalk." (PMID 34439397, 2021). "Thromboxane A2 receptor signaling pathway has been hailed as an emerging paradigm in cancer progression and metastasis." (PMID 33945541, 2021). "Moreover, the data suggest TBXA2R expression is elevated to a greater extent in some cancers (such as CML, meningioma, AML, mesothelioma and renal cancer) where the significance is yet to be determined." (PMID 36234768, 2022). "It is noteworthy in this respect, that the genes showing the strongest signals of negative selection include several plasma membrane receptor proteins (e.g. ACKR3, CCR2, CCR5, CX3CR1, TBXA2R) that cancer cells utilize to promote migration, invasion, and metastasis." (PMID 33427197, 2021). "Taken together, these data suggest that ALA and ARA oxidative derivatives may have distinct and possibly opposite effects on cancer cell properties that may be, at least in part, mediated by TBXA2R." (PMID 31905626, 2019). "This indicates that metabolites generated by TBXAS1 may play a very different role in cancer to that of TBXA2R." (PMID 16250911, 2005). "What was not previously apparent is the high degree of correlation between TBXA2R and TBXAS1 expression across all tumors in the TCGA pan-cancer dataset (Pearson co-efficient 0.58; p < 0.0001)." (PMID 36234768, 2022). "Thromboxane synthase (TXAS) and thromboxane A2 receptor (TP), two critical components for thromboxane A2 (TXA2) signaling, have been suggested to be involved in cancer invasion and metastasis." (PMID 23349788, 2013). "This together with the current study indicates that TBXA2R, has a potential impact, via its metabolised product TAX2, on the metastatic nature of cancer cells." (PMID 16250911, 2005). "Our analysis of human methylation in the TBXA2R promoter (first 1 kb) revealed little evidence of epigenetic regulation in cancer, as the correlation of mRNA and promoter methylation is relatively poor (R2= 0.029)." (PMID 36234768, 2022). "Using the non-redundant pan-cancer studies database (TCGA, 32 cancer types, 59, 132 patients), we determined that TP mRNA expression is inversely correlated with TBXA2R promoter methylation across 23 different cancers." (PMID 36234768, 2022). "Of these cancers, at least AML and CML also had significant TBXA2R expression." (PMID 36234768, 2022).
tumor (12 papers, 2005 to 2025). "We have also shown for the first time that TBXA2R is transcriptionally repressed by BRCA1 (a tumour suppressor often mutated or down-regulated in TNBC), providing a potential mechanism by which TBXA2R is up-regulated in TNBC/BLBCs." (PMID 27487152, 2016). "While TBXA2R is commonly expressed in tumours and particularly in aggressive tumours, TBXAS1, in contrast, showed a very different expression pattern from that of TBXA2R." (PMID 16250911, 2005). "When normal mammary tissues and tumour tissues were compared, TBXA2R was found to be higher in tumour tissues than in normal tissues, although this is not statistically significant (p = 0.09)." (PMID 16250911, 2005). "While TBXA2R is highly expressed in aggressive tumours and linked with poor prognosis, TBXAS1 is expressed at significantly low levels in high grade tumours and tumour patients with poor prognosis." (PMID 16250911, 2005). "We internally validated immunohistochemical (IHC) staining for TBXA2R and performed IHC on an in-house tissue microarray containing 63 TNBC cases (3 tumour cores from each case) with 5 year clinical follow-up." (PMID 27487152, 2016). "While TBXA2R is normally expressed in tumours and particularly in aggressive tumours, TBXAS1, however, showed a very different expression pattern from that of TBXA2R." (PMID 16250911, 2005). "In the current study, we have observed that there was significant correlation between levels of TBXA2R and TBXAS1 and tumour grade." (PMID 16250911, 2005). "Ifetroban reduces metastasis in the absence of a primary tumor or when TBXA2R is deleted from tumor cells." (PMID 41233835, 2025). "TPr inhibition in platelets appears to be a prominent mechanism of ifetroban’s antimetastatic activity, particularly since ifetroban prevents metastasis in the absence of a primary tumor or in TBXA2R deleted cells." (PMID 41233835, 2025). "For instance, COX‐2 expression is upregulated in a variety of tumor cells, and its downstream metabolite TXA2 binds to the G‐protein‐coupled receptors P2Y and TBXA2R on the surface of platelets, inducing platelet activation to bind to tumor cells and promoting their hematogenous metastasis." (PMID 37719444, 2023). "Inspection of the data of De Kegel and Ryan, 2019 shows that ACKR3, CX3CR1, TBXA2R were not assigned to the essential category in any of the 558 tumor cell lines tested." (PMID 33427197, 2021). "However, TBXA2R expression was significantly increased in grade 3 tumours(p = 0.006 vs grade 1), while TBXAS1 was significantly reduced in grade 3 tumours (p = 0.026 vs grade 1 tumours)." (PMID 16250911, 2005). "ER positive tumours had significantly higher levels of TBXA2R compared with ER negative tumours (p=0.0128)." (PMID 16250911, 2005). "Finally, the current study has shown that ER positive tumours have significantly higher TBXA2R levels than ER negative tumours." (PMID 16250911, 2005). "A similar differential expression pattern was seen in tumours from patients with different prognosis, in that patients with predicted poor prognosis had higher, but not statistically different, levels of TBXA2R, and significantly lower levels of TBXAS1 (p = 0.008)." (PMID 16250911, 2005). "To further isolate the contributions of tumor cell TPr and platelet TPr to the antimetastatic efficacy of ifetroban, we conducted additional studies in an experimental hematogenous model of metastasis lacking a primary tumor and using TBXA2R-deleted tumor cells." (PMID 41233835, 2025).
cardiovascular disease (5 papers, 2017 to 2024). "Differential expression of ITGB3 and TBXA2R between two groups was associated with the platelet activation pathway and cardiovascular disease." (PMID 39273193, 2024). "From this result, two lncRNAs AP001033.3–201 and AC068234.2–202, and two potential target genes, integrin beta-3 (ITGB3) and thromboxane A2 receptor (TBXA2R), were identified to be associated with cardiovascular disease and involved in the platelet activation pathway." (PMID 33172104, 2020). "Alterations in TBXA2R distribution have been observed in various cardiovascular diseases, contributing to pathophysiological processes." (PMID 39273193, 2024). "Its main cause is cardiovascular diseases (CVD), in which increased biosynthesis of TxA2 and isoprostanes, as well as increased activation of the thromboxane A2 receptor (TXA2R), are observed." (PMID 34769074, 2021). "Finally, the study results indicated that ITGB3 and TBXA2R were both differentially expressed between the two groups and were both related to the platelet activation pathway and cardiovascular disease in a GO enrichment analysis." (PMID 32723322, 2020). "However, the distribution of TBXA2R is altered in various cardiovascular diseases and is involved in pathophysiological processes." (PMID 32723322, 2020).
colonic polyps (1 paper, 2015). "Our immunohistochemistry staining results clearly showed that both TBXA2R and TBXAS1 were highly expressed in most colonic polyps or tumors, but not in normal colorectal tissues." (PMID 25750933, 2015).
TBXA2R also shares sentences with these, for which no sentence is quoted: cerebral infarction (3 papers); adenocarcinoma (2); lung carcinoma (2); acute coronary syndrome (1); Allergy (1); aneurysm (1); aortic aneurysm (1); arteriosclerosis (1); atrial fibrillation (1); brain injury (1); cardiac hypertrophy (1); chronic kidney disease (1); dermatitis (1); hepatocellular carcinoma (1); hypopharyngeal cancers (1); hypospadias (1); immune dysfunctions (1); inflammatory breast carcinoma (1); intestinal polyp (1); laryngeal carcinoma (1); left ventricular hypertrophy (1); lupus (1); metabolic disease (1); myocardial infarction (1); oral cancers (1); ovarian tumors (1); polycythemia (1); rhinitis (1); septic shock (1); Shock (1).
A further 4 diseases each share a sentence with TBXA2R in 1 paper.